SLC36A3 (solute carrier family 36 member 3)
Synonyms: PAT3; TRAMD2; tramdorin2
Tractability: Antibody: UniProt predicts a signal peptide or a membrane-spanning region.
Gene: Protein-coding gene on chromosome 5 (151,276,358 to 151,303,766, reverse strand). Ensembl gene ENSG00000186334.
Subcellular location: Membrane
Gene Ontology:
Molecular function: amino acid:proton symporter activity; glycine transmembrane transporter activity; L-alanine transmembrane transporter activity; L-proline transmembrane transporter activity
Biological process: glycine transport; L-alanine transport; proline transmembrane transport; proton transmembrane transport
Cellular component: membrane
Genetic constraint (gnomAD): Loss-of-function variants: 32 observed, 42.15 expected, observed/expected ratio (o/e) 0.76, 90% interval 0.57 to 1.02. The upper end of that interval is the gene's LOEUF score, 1.02, which puts it in group 4 of 6, group 1 being the genes least tolerant of losing a copy. Missense variants: 520 observed, 587.67 expected, observed/expected ratio (o/e) 0.88, 90% interval 0.82 to 0.95. Synonymous variants: 205 observed, 232.02 expected, observed/expected ratio (o/e) 0.88, 90% interval 0.79 to 0.99.
Homologues: Orthologues: chimpanzee SLC36A3 (99% identical), macaque SLC36A3 (96% identical), pig SLC36A3 (88% identical), rabbit SLC36A3 (84% identical), guinea pig SLC36A3 (78% identical), mouse Slc36a3 (74% identical), rat Slc36a3 (74% identical), Drosophila melanogaster CG13384 (36% identical), Drosophila melanogaster CG16700 (32% identical), Drosophila melanogaster CG7888 (30% identical), Drosophila melanogaster acs (30% identical), Drosophila melanogaster CG4991 (28% identical), and 13 more. Paralogues in human: SLC36A1 (61% identical), SLC36A2 (57% identical), SLC36A4 (47% identical), SLC38A4 (19% identical), SLC38A2 (19% identical), SLC38A1 (18% identical), SLC38A3 (18% identical), SLC38A5 (17% identical), SLC38A6 (17% identical), SLC32A1 (17% identical), SLC38A10 (16% identical), SLC38A9 (16% identical), and 3 more.
Diseases named in the same sentence as SLC36A3 in open-access papers:
SLC36A3 is named in the same sentence as 2 diseases in open-access papers, as found by Europe PMC text mining. Sharing a sentence is not in itself a finding about the gene and the disease.
SLC36A3 shares sentences with these, for which no sentence is quoted: Tay-Sachs disease (1 paper); tumor (1).